DYRK1A (dual specificity tyrosine phosphorylation regulated kinase 1A)
Diseases named in the same sentence as DYRK1A in open-access papers (continued):
Sharing a sentence is not in itself a finding about the gene and the disease.
glioma (16 papers, 2016 to 2025). A benign or malignant brain and spinal cord tumor that arises from glial cells (astrocytes, oligodendrocytes, ependymal cells). "To further explore the effect of Dyrk1A on the cell apoptosis, we performed overexpression and knockdown of Dyrk1A in U87 cells (Human glioma cell line) and then treated the cells with 1.2 mM or 1.5 mM H2O2 for 2 h to induce apoptosis." (PMID 37864462, 2024). "In gliomas, the expression of DYRK3 and CLK3 correlated with worse survival, while DYRK1A, DYRK2 and CLK1 were associated with better disease outcomes." (PMID 38398225, 2024). "Another study found that DYRK1A and DYRK1B kinases phosphorylate ID2 on threonine 27 (Thr27), leading to HIF2α destabilization, loss of glioma stemness and inhibition of tumour growth." (PMID 34109727, 2021). "Our data demonstrate that NFATC1 and DYRK1A proteins are highly expressed in gliomas, particularly in grade 4 gliomas (GBM)." (PMID 34309232, 2021). "In the gliomas, high expression of DYRK1A correlates with epidermal growth factor receptor (EGFR) expression." (PMID 34117217, 2021). "DYRK1A prevents endocytotic degradation of EGFR through phosphorylation of the EGFR-signaling modulator Sprouty 2 (SPRY2) and DYRK1A inhibition leads to reduced glioma growth." (PMID 34117217, 2021). "As has been previously suggested, our results also show that DYRK1A inhibition suppresses the growth and migration of glioma cells." (PMID 34117217, 2021). "NFATC1 expression was also correlated with DYRK1A expression in glioma cell lines." (PMID 34309232, 2021). "Our results suggest that DYRK1A is a potential therapeutic target for glioma migration." (PMID 34309232, 2021). "We propose that the recovery of NFATC1 stability is a key oncogenic event in a large proportion of gliomas, and pharmacological inhibition of DYRK1A by polypeptides could represent a promising therapeutic intervention for GBM." (PMID 34309232, 2021). "DYRK1A was highly expressed in both the cytosol and nucleus of grade 4 glioma cells." (PMID 34309232, 2021). "Higher expression of NFATC1 and DYRK1A proteins was also observed in several glioma cell lines." (PMID 34309232, 2021). "We propose that the recovery of NFATc1 stability is a key oncogenic event in a large proportion of gliomas and polypeptide pharmacological inhibition of DYRK1A could represent a promising therapeutic intervention for NFATc1‐dependent GBM." (PMID 34309232, 2021). "To examine whether NFATC1 is affected by DYRK1A in glioma cells, we measured the protein levels of NFATC1 in T98G cells." (PMID 34309232, 2021). "Further, silencing of DYRK1A inhibits the growth of glioma cells mediated by TRAF2." (PMID 34117217, 2021). "To test whether TRAF2 can regulate the stability of EGFR in glioma cells, we performed knockdown of DYRK1A and TRAF2 in human glioma cell lines U251 and A172, and analyzed the protein level of EGFR." (PMID 34117217, 2021). "DYRK1A and DICER1 are involved in neural development and miRNA processing, both of which are dysregulated in glioma." (PMID 40561176, 2025). "Our data suggest a synergistic effect of DYRK1A and NFATC1 on glioma cell migration and tumor metastasis." (PMID 34309232, 2021). "Silencing of DYRK1A or TRAF2 increases EGFR degradation and inhibition of the growth of glioma cells." (PMID 34708541, 2021). "Protein levels of DYRK1A and NFATC1 were examined in normal tissues and gliomas of different grades using tissue arrays and IHC analysis." (PMID 34309232, 2021). "Correlated expression of DYRK1A and NFATC1 proteins was observed in both glioma tissues and glioma cell lines." (PMID 34309232, 2021). "Our results show that inhibition of DYRK1A by NFATC1‐P3 polypeptides significantly destabilizes NFATC1 protein levels and reduces T98G glioma cell migration." (PMID 34309232, 2021). "In contrast, in glioma stem cells, one of the human HIF−1 homologs, HIF-2α/EPAS1, is inhibited by DYRK1A/B in a VHL-dependent manner." (PMID 28562327, 2017).
glioma (continued). "Moreover, DYRK1A and NFATC1 synergistically increased T98G glioma cell migration." (PMID 34309232, 2021). "As an alternative, we considered DYRK1A (dual-specificity tyrosine phosphorylation-regulated kinase 1A), as we have previously demonstrated that this kinase promotes the stability of EGFR in adult neural progenitors and glioma cells, where it controls the growth and the survival of the tumors." (PMID 31947645, 2020). "Indeed, DYRK1A and EGFR protein levels correlate in tissues from glioma patients." (PMID 32751160, 2020).
trisomy 21 (16 papers, 2011 to 2026). A chromosomal disorder consisting of the presence of an extra chromosome 21. "Observations in mouse models with dosage imbalance of Dyrk1a lead to a hypothesis that a reduction of Dyrk1a, as in DYRK1A syndrome, and an increase of Dyrk1a, as in Trisomy 21, both cause skeletal deficits, providing a foundation for the study of these phenotypes in humans." (PMID 39308945, 2024). "Our results demonstrate that Leucettinib-21, a potent and selective low-molecular weight pharmacological inhibitor of DYRK1A, decreases DYRK1A activity in human trisomy 21 neural progenitor cells and cortical neurons." (PMID 41676546, 2026). "Trisomy 21 results in overexpression of key genes (e.g., DYRK1A, RCAN1) involved in neural plasticity and oxidative stress regulation, compounding neurodevelopmental delays." (PMID 41383574, 2025). "For this reason, the emphasis of DYRK1A research has been on its role in trisomy 21 and neurological dysfunction." (PMID 21364930, 2011). "As a result of trisomy 21, there is a 1.5-fold increase in DYRK1A mRNA and protein levels." (PMID 39850411, 2025). "Several mechanisms for DYRK1A function in Trisomy 21 have been proposed." (PMID 37607329, 2023). "Therefore, DYRK1A inhibition may present a therapeutic intervention for Trisomy 21, with the potential to manage and/or reverse adverse neurological symptoms, including the increased risk of neurofibrillary degeneration and the development of dementia." (PMID 37607329, 2023). "However, the mechanism underpinning DYRK1A involvement in Trisomy 21-related pathological tau aggregation remains unknown." (PMID 33380426, 2021).
developmental delay (15 papers, 2008 to 2025). "Although haploinsufficiency of Dyrk1A also causes severe neurological symptoms and developmental delay, these pharmacological inhibitors, when dosed well, appear to rescue Dyrk1A hyperactivity phenotypes only down to the WT level." (PMID 34090874, 2021). "Together, our results suggest that the novel heterozygous mutation of DYRK1A resulted in loss-of-function of the kinase activity of DYRK1A and may contribute to the developmental delay observed in the patient." (PMID 32555303, 2020).
leukemia (15 papers, 2008 to 2025). A malignant (clonal) hematologic disorder, involving hematopoietic stem cells and characterized by the presence of primitive or atypical myeloid or lymphoid cells in the bone marrow and the blood. "This is particularly relevant for B- and T-cells, where dysregulation of DYRK1A–i.e., due to T21– may underly important pathogenic outcomes associated with DS, such as uncontrolled (auto-) inflammatory conditions or leukemia (see next sections)." (PMID 40519271, 2025). "Hence, how DYRK1A contributes to the hyperinflammatory state of people with DS, and how these dysregulated mechanisms reinforce DS-associated leukemias should be the focus of future efforts." (PMID 40519271, 2025). "Results from in vitro drug combination testing are promising, and future directions should consider clinical evaluation in early phase trials for leukaemia, as well as for tumours with poor prognosis, such as glioblastoma or head and neck cancer, where DYRK1A has also been implicated." (PMID 38999925, 2024). "Finally, DYRK1A could play a potential role in the regulation of other Hsa21-encoded genes implicated in DS-associated leukemias, like RUNX1 and RCAN1." (PMID 40519271, 2025). "Here, we present a detailed review of the literature summarizing all the information linking DYRK1A to blood and immune function, as well as leukemia, inflammation and viral infections, with a special focus on their potential associations to T21." (PMID 40519271, 2025). "To identify new targets in KMT2A-R ALL for precision medicine approaches, we performed a kinome-wide CRISPR screen and identified multiple kinases, including DYRK1A, as required for leukemia cell survival." (PMID 40148558, 2025). "Here, we present a detailed review of the literature reporting on specific roles of DYRK1A in blood and immune cell development and function, as well as in leukemia, inflammatory disorders, and viral infections." (PMID 40519271, 2025). "BCP-ALL cells expressed high levels of BAFFR, which activated the non-canonical NF-kB (ncNF-kB) pathway in response to BAFF in a DYRK1A-dependent manner to maintain the survival of leukemia cells." (PMID 40695793, 2025). "We also performed a gain-of-function meta-analysis of an Eμ-myc transgenic lymphoma/leukemia model and observed that increased Myc levels correlate with decreased Dyrk1a levels during in vivo leukemia progression, further confirming a negative regulation of Dyrk1a via Myc." (PMID 40148558, 2025). "Itappears that serine phosphorylation of this motif through the involvement ofone of the serine/threonine kinases, such as Dyrk1A, may contribute to theprogression of the leukemia." (PMID 40771845, 2025). "Our preclinical data suggest that co-targeting of DYRK1A and menin or BCL2 has particular activity against this high-risk leukemia subtype that may warrant clinical investigation in patients in the future to address issues of chemoresistance and relapse risk." (PMID 40148558, 2025). "However, despite numerous research reports in recent years, the role of DYRK1A in cancer and leukemia, in the context of DS, is still very unclear as both oncogenic and tumor suppressive roles have been reported." (PMID 36012629, 2022). "There is abundant literature linking DYRK1A with solid cancers and leukemias (reviews:)." (PMID 34205123, 2021). "These surprising results suggest that DYRK1A and GATA1 may synergistically restrain megakaryocyte proliferation in T21 and that DYRK1A inhibition may not be a therapeutic option for GATA1s-associated leukemias." (PMID 37906251, 2023). "We further observed that pharmacologic DYRK1A inhibition markedly reduced human KMT2A-R ALL cell proliferation in vitro and potently decreased leukemia proliferation in vivo in drug-treated patient-derived xenograft mouse models." (PMID 40148558, 2025).
leukemia (continued). "Our results demonstrate that KMT2A-R ALL requires DYRK1A for normal cell proliferation and dual inhibition of DYRK1A and BCL2 decreases leukemia progression in KMT2A-R ALL PDX models." (PMID 40148558, 2025). "Herein, we demonstrate an unanticipated direct regulation of DYRK1A via oncogenic KMT2A rearrangements in ALL and a specific requirement of DYRK1A for leukemia proliferation." (PMID 40148558, 2025). "DYRK1A has been found to phosphorylate STAT3 Ser-727 in a simian fibroblast (COS-7) cell line and in human B cell precursor of leukemia (MUTZ-5) cells." (PMID 34828406, 2021). "Analysing the expression of potent kinase off-targets of PARP inhibitors in haematological cancers using canSAR53 reveals that DYRK1A and DYRK1B are overexpressed at the mRNA level in several types of leukaemia and lymphoma." (PMID 32066817, 2020). "We next tested the DYRK1A protein levels across different subtypes of ALL and AML and, interestingly, observed increased DYRK1A expression in KMT2A-R ALL compared to the tested KMT2A wild-type leukemia cell lines and PDX cases." (PMID 40148558, 2025). "In conclusion, several lines of evidence support direct and complementary roles for DYRK1A in leukemia, both in people with and without T21, and highlight its inhibition as a novel therapeutic opportunity against these malignancies." (PMID 40519271, 2025). "Through the identification of new dosage-sensitive genes in children with DS and leukaemia, several groups have shown that targeting the product of the chromosome 21 genes HMGN1 and DYRK1A may be broadly applicable to many blood cancers and potentially solid tumours." (PMID 38999925, 2024). "Notably, DS mice do not develop leukemia when crossed with GATA1s mice, underscoring the importance of studying the function of DYRK1A in human cell models." (PMID 37906251, 2023).
neuroblastoma (14 papers, 2017 to 2025). Neuroblastoma (NB) is the most common solid, extracranial childhood tumor. "DYRK1A has been shown to extend the G1 phase of the cell cycle in neuroblastoma cells by phosphorylation and subsequent degradation of cyclin D1." (PMID 39436397, 2024). "Stimulation of DYRK1A mRNA by Aβ peptides in neuroblastoma cells demonstrate that Aβ increases expression of DYRK1A." (PMID 37808474, 2023). "EGCG disrupted the growth of SH-SY5Y immature neuroblastoma by targeting the dual specificity tyrosine-phosphorylation-regulated kinase 1A (DYRK1A) in vitro." (PMID 37048059, 2023). "We noticed that 3D Matrigel-based neuroblastoma model shows the influence of DYRK1A inhibition on the 3D culture growth." (PMID 33860868, 2021). "Reduced incidence of solid tumors such as neuroblastoma in DS patients and increased vascular anomalies in DS fetuses suggest a potential role of DYRK1A in angiogenic processes, but in vivo evidence is still scarce." (PMID 31043432, 2019). "Therefore, we knocked down DYRK1A in the human neuroblastoma cell line SH-SY5Y and observed a significant reduction in cell size." (PMID 39436397, 2024). "EGCG inhibited DYRK1A in Matrigel 2D and 3D-cultured neuroblastoma cell SH-SY5Y." (PMID 33860868, 2021). "In this study, we found the DYRK1A inhibitor EGCG impaired neuroblastoma growth, suggesting that DYRK1A could be a therapeutic target and EGCG is a potential anti-cancer drug." (PMID 33860868, 2021). "This increase of DYRK1A expression could be attributed to Aβ, since Aβ treatment increased DYRK1A transcript levels in neuroblastoma cells." (PMID 29215943, 2018). "To confirm the effects of the active products on native DYRK1A in a cellular context, we made use of a SH-SY5Y neuroblastoma cell line expressing human DYRK1A and antibodies directed against cyclin D1 phosphorylated at Threonine 286, a reported DYRK1A phosphorylation site." (PMID 29039762, 2017). "Likewise, the Aβ peptide has been reported to induce an increment of DYRK1A mRNA levels and to lead to τ phosphorylation at Thr212 under τ overexpression in neuroblastoma cells, suggesting DYRK1A as a key molecule bridging Aβ production and τ phosphorylation in AD." (PMID 34445804, 2021). "The DYRK1A inhibiting nature of EGCG, together with the facts that EGCG inhibits the growth and induces the differentiation of neuroblastoma in vitro models, suggests an oncogene role of DRYK1A." (PMID 33860868, 2021). "Dyrk1A stabilizes p27 and induces cell cycle exit and neuronal differentiation in SH-SY5Y neuroblastoma cells, but the in vivo function of this Dyrk1A-mediated regulation of p27 is still unclear." (PMID 31080801, 2019).
Parkinson disease (13 papers, 2016 to 2026). A progressive degenerative disorder of the central nervous system characterized by loss of dopamine producing neurons in the substantia nigra and the presence of Lewy bodies in the substantia nigra and locus coeruleus. "Abnormal expression and activity of Dyrk1A levels was found to occur in neurodegenerative diseases such as Alzheimer's and Parkinson's diseases and induces loss of neurons." (PMID 34121317, 2021). "Dysregulation of DYRK1A often leads to severe NGDs, such as Parkinson’s disease, DS, and AD, indicating that targeting DYRK1A for drug design holds great potential." (PMID 39494990, 2024). "DYRK1A phosphorylates α-synuclein, a major component of the Lewi bodies (LB) that are found in several neurodegenerative disorders including Parkinson’s disease (PD), dementia with LB and AD, enhancing its aggregation within the cytoplasm of neurons and glial cells." (PMID 34828439, 2021). "In addition to its significance in DS, the overexpression or hyperactivity of DYRK1A has been also reported in the brains of individuals diagnosed with any one of several neurodegenerative diseases, including AD, Parkinson's, Huntington's and Pick's." (PMID 27483355, 2016).